DKK3 (dickkopf Wnt signaling pathway inhibitor 3)
Diseases named in the same sentence as DKK3 in open-access papers (continued):
Sharing a sentence is not in itself a finding about the gene and the disease.
cancer (continued). "DKK3 may modulate cancer cell malignant potentials by activating AKT thorough the binding of DKK3 to RTK or Wnt receptors and by intracellular protein-protein interactions of DKK3b." (PMID 36033456, 2022). "Taken together, DKK3 may determine oncogenic properties in DKK3-expressing cancers; therefore, it is a promising therapeutic target for such cancers." (PMID 36376957, 2022). "DKK3 is frequently downregulated in various cancers, and therefore, this study supports the hypothesis that downregulation of DKK3 occurs commonly during carcinogenesis." (PMID 35205672, 2022). "In this context, we have pursued the cancer-specific molecules that could be possible druggable targets, and have focused on the DKK3 gene." (PMID 36376957, 2022). "Dkk-3 is a secreted protein with context-dependent functions in several types of cancer." (PMID 36497305, 2022). "Hence, developing human secreted DKK3 as a biotherapeutic molecule, in cancer treatment, will be added in our future work." (PMID 35205672, 2022). "Taken together, we believe that DKK3 may be a promising cancer therapeutic for overcoming drug resistance, which may be utilized in various types of biopharmaceutics." (PMID 35205672, 2022). "In addition, we identified that navitoclax (ABT-263) affected GBM cancer cell lines with high DKK3 expression." (PMID 35599254, 2022). "We suspected that Cabergoline repressed the activity of the natural inhibitor of the Wnt/β-catenin pathway, DKK-3, which is reported to exert significant antitumor efficacy by suppressing the activity of the Wnt/β-catenin pathway in multiple types of malignant tumors." (PMID 34592907, 2021). "Dkk3 mRNA expression levels were lower in cancer than in normal tissues (p<0.05)." (PMID 33425757, 2020). "Notably, it has been observed that reducing and/or silencing Dkk3 is closely related to a broad range of cancer cell types, including BC 7,8." (PMID 32284738, 2020). "Nicola confirmed that Kremen-1, but not lipoprotein receptor-related protein 6 (LRP6), immunoprecipitated with DKK3 in cancer-associated fibroblasts, and the mRNA levels of Kremen-1 were not altered after DKK3 silencing." (PMID 32331523, 2020). "Dkk3 protein expression levels were lower in cancer than in normal tissues (p<0.05)." (PMID 33425757, 2020). "The epigenetic loss of DKK3 expression activates TGF-β signaling, leading to increased expression of pro-invasive factors, such as TGFBI and MMP2, which have the potential to promote progression to cancer." (PMID 29858602, 2018). "Analysis of intracellular product of the Dkk3 gene, revealed that DKK3b arrests Wnt stimulated cell proliferation and selectively silences ß-catenin dependent gene expression in both immortal and cancer cells." (PMID 28738084, 2017). "The molecular events mediating the DKK3-dependent arrest of ß-catenin-driven cell proliferation in cancer cells are unknown." (PMID 28738084, 2017). "However, the physiological significance of altered Dkk-3 expression in cancer and its potential growth inhibitory outcome are unidentified." (PMID 28978116, 2017). "However, hypermethylation of the DKK3 promoter region suppresses its expression in many cancer cells, including hepatocarinoma." (PMID 27788486, 2016). "Downregulation of endogenous Dkk-3/REIC is frequently observed in most cancers." (PMID 27827955, 2016). "DKK3 is significantly down-regulated in a broad range of cancer cell types." (PMID 26378036, 2015). "However, an elevated protein expression level in the endothelial cells of microvessels of cancer tissue has also been reported indicating the potential importance of DKK3 in CRC progression, due to angiogenesis and neovascularisation." (PMID 25793510, 2015). "In addition, the direct cytotoxic effects of exogenous REIC/Dkk-3 protein were examined in several cancer cell lines." (PMID 24527065, 2014).
cancer (continued). "The differences in the capacity for REIC/Dkk-3 gene overexpression between cancer and normal cells may explain the cancer cell-specific apoptosis induced by Ad-REIC." (PMID 24527065, 2014). "Reduced DKK3 expression has been reported in various types of cancers, but its functions and related molecular mechanisms in breast tumorigenesis remain unclear." (PMID 23890219, 2013). "Dkk-3/REIC expression has been shown to be downregulated in multiple cancer cell lines although its exact oncogenic suppressive mechanism is still unknown." (PMID 23476112, 2013). "An impact of DKK3 promoter methylation on cancer patient survival has been repeatedly found." (PMID 18826564, 2008). "Furthermore, through staining for DKK3 using tissue microarrays and genetically engineered mouse models (GEMMs), we demonstrated elevated expression levels in acinar cells and PanINs in comparison to carcinoma." (PMID 41147409, 2026). "Moreover, we believe that in cancer, DKK3 can act as both a tumor suppressor gene and an oncogene." (PMID 37149563, 2023). "Also, the role of DKK3 in tumorigenesis varies in different cancers." (PMID 35796776, 2023). "Thus, REIC/Dkk-3 contributes to the induction of cancer vulnerability against immune cells." (PMID 36869893, 2023). "These diseases may confound attempts to use the detection of Dkk-3 to monitor cancer progression." (PMID 36497305, 2022). "Moreover, as a soluble Wnt inhibitor, most knowledge about Dkk3 involves molecular cancer therapy." (PMID 32590948, 2020). "Thus, our data build on previous studies on the regulation of DKK3 by miR-92a in human cancers." (PMID 30926679, 2019). "Thus, it may be possible to develop new therapies that re-activate Dkk-3 expression or that activate the Dkk-3 signal in cancer cells." (PMID 29843383, 2018). "Dkk3 behaves as an oncosuppressor protein by inducing apoptotic death in a variety of cancers, although it might favor cancer cell spreading by promoting angiogenesis." (PMID 30258353, 2018). "Additionally, DKK3 may play a different role in the survival of HNSCC patients compared to other types of cancer." (PMID 28708091, 2017). "Accordingly, downregulation of DKK3 may differ with different cancer types." (PMID 28708091, 2017). "Furthermore, ectopic expression of DKK3 in a variety of cancer cell types stifled aggressive malignant behavior, reversed epithelial-mesenchymal transition (EMT), and impaired cell motility, pointing towards a comprehensive dedifferentiation-blocking role for DKK3." (PMID 28249601, 2017). "DKK3 and BMP1 treatment in cancer cells; dormancy confirmed by live-cell imaging and co-staining for Ki-67-/p27+; p-p38 nuclear translocation assessed by IF." (PMID 41404065, 2025). "The miRNAs targeted the WNT antagonist Dickkopf WNT signaling pathway inhibitor 3 (DKK3) and the Notch suppressor Endocytic Adaptor Protein (NUMB) in the cancer cells that remained viable following chemotherapy." (PMID 39703687, 2024). "When REIC/Dkk-3 is overexpressed with the use of a gene-engineered adenovirus-REIC/Dkk-3 expression vector (hereinafter Ad-REIC), REIC/Dkk-3 induces apoptotic cell death in cancer cells while sparing normal cells." (PMID 36869893, 2023). "While evidence about the link between DKK3 and immune response in cancers was sparse, few reports showed an immunomodulatory role and a possible therapeutic effect of REIC/DKK3 in some cancers through stimulation of the immune system." (PMID 36845147, 2023). "Due to the dominant expression of CMTM6 among the proteins in cancer cells, we next focused on CMTM6 and observed that REIC/Dkk-3 competed with CMTM6 for PD-L1, thereby liberating PD-L1 from its complexation with CMTM6." (PMID 36869893, 2023). "The cancer-suppressing mechanisms of the REIC/DKK-3 gene depend on multiple pathways that exert both direct and indirect effects on cancers." (PMID 36869893, 2023).
cancer (continued). "The same group demonstrated that miR-25-3p silences the Dickkopf WNT signaling pathway inhibitor 3 (DKK3) gene, thus supporting in vitro cancer growth and resistance to different chemotherapeutics [methotrexate, cisplatin, doxorubicin, and docetaxel (DOC)]." (PMID 35814444, 2022). "Through the GDSC database containing information on drug screening of cancer cell lines, we were able to investigate drug sensitivity in GBM cell lines according to DKK3 expression." (PMID 35599254, 2022). "Overall, these data supported a model where HSF1 in CAFs leads to DKK3 upregulation, which in turn potentiates YAP/TAZ activity leading to increased ECM remodelling and promotion of cancer cell growth and invasion." (PMID 30631061, 2019). "Of note, the Dickkopf-related protein 3 (DKK3) gene, also known as ‘reduced expression in immortalized cells’ (REIC), is remarkably silenced by promoter methylation in many types of cancer, including PCa, particularly in high Gleason grade tumors." (PMID 29843383, 2018). "We examined DNA methylation levels of SFRP1, SFRP2, SFRP5, DKK2, DKK3, mir34b/c, RASSF1A, IGFBP7, CDKN2A, and MLH1 in cancerous glands and normal crypts isolated from cancer tissue and the surrounding normal mucosa." (PMID 28533824, 2017). "It has been showed that the overexpression of adenovirus-mediated REIC/Dkk-3 (Ad-REIC) acted via c-Jun-NH2-kinase (JNK) and c-Jun to induce apoptosis in cancer cells." (PMID 28978116, 2017). "Compared to surrounding normal colonic crypts, the methylation levels of SFRP1, SFRP2, SFRP5, DKK2, DKK3, mir34b/c, and RASSF1A in MSS CRCs were significantly higher in cancer crypts." (PMID 28533824, 2017). "In all the cancer cell lines tested in this study, the Ad-SGE-REIC was superior to conventional adenoviral systems in terms of the REIC/Dkk-3 protein expression and in vitro induction of apoptosis." (PMID 24398705, 2014). "At the same time, abundant TAA fragments are released as a result of cancer cell-selective apoptosis and supplied to the DCs induced by the secreted REIC/Dkk-3 protein." (PMID 24527065, 2014). "The expression of REIC/Dkk-3 is significantly downregulated in a wide range of human cancer types, making REIC/Dkk-3 a promising cancer therapeutic gene." (PMID 24398705, 2014). "The reduced expression in immortalized cells (REIC) gene is identical to Dickkopf (DKK)-3 and REIC/Dkk-3 expression is significantly downregulated in a broad range of human cancer cells." (PMID 24527065, 2014). "Results showed ∼40–80% reduction in colony formation in DKK3-transfected MB231 and BT549 cancer cells, compared to controls (P < 0.01)." (PMID 23890219, 2013). "While most studies investigated the role of DKK3 in established cancers, none of these specifically explored its role during cancer initiation." (PMID 41147409, 2026). "Again, no genotype‐specific sensitizing effect was induced upon MEK inhibition, indicating that this pathway lost its genotype‐specific relevance upon cancer progression in the absence of DKK3." (PMID 41147409, 2026). "In this study, we explored the prognostic value of DKK3, ECM-1 and TGFB1 using a bioinformatical approach through analysis of large publicly available datasets from The Cancer Genome Atlas Program (TGCA) and Pan-Cancer Atlas databases." (PMID 38855324, 2024). "The cancer PD-L1 is able to dampen not only T cells but also NK cells because these cells consistently express PD-1, and we therefore examined the effect of REIC/Dkk-3 on NK cells in vitro." (PMID 36869893, 2023). "We conducted the present study to clarify the anticancer role of the REIC/Dkk-3-receptor(s) axis, the precise knowledge of which would contribute to our understanding of the physiological roles of the REIC/Dkk-3 protein and would also provide further evidence that Ad-REIC mediates cancer effects." (PMID 36869893, 2023). "Dkk-3 appears to play a beneficial role for patients in many, but not all cancers, and how it functions remains poorly understood." (PMID 36497305, 2022).
cancer (continued). "Emerging evidence indicates DKK3 is downregulated in various cancer tissues, including renal clear cell carcinoma, non-small cell lung cancer and uterine cervical squamous cell carcinoma." (PMID 35924156, 2022). "In addition, these cells express dickkopf-3 (DKK-3), dickkopf-1 (DKK-1), and insulin-like growth factor-binding protein 3 (IGFBP-3), which significantly inhibit the proliferation of cancer cells and increase the apoptosis rate of HepG2 cells." (PMID 35406638, 2022). "We identified cancer-specific genes in HNSCC and focused on DKK3 expression." (PMID 36376957, 2022). "Because our aim of this study was to elucidate the implication of aging on carcinogenesis, we then assessed the correlation of age with TBX3 and DKK3 expression in patients without cancer." (PMID 36923312, 2022). "DKK3 expression was higher in GBM, a more severe cancer, than in LGG, a less severe cancer." (PMID 35599254, 2022). "The elevated expression of both DKK1 and DKK3 in carcinoma tissues of HCC patients as compared to non-carcinoma tissues have been reported." (PMID 33562077, 2021). "Our bioinformatics data showed higher Dkk3 expression in CAF than in CD133+ or in CD133- cancer cells, supporting the hypothesis that Dkk3 in cancer stromal cells might be involved in cancer progression." (PMID 33425757, 2020). "DKK‐3,20, 21 DKK‐122 and IGFBP‐323, 24 are potent inducers of apoptosis in cancer cells." (PMID 32798252, 2020). "DKK3, also known as Reduced Expression in Immortalized Cells (REIC), has been deemed to function as an important cancer suppressor which down-regulated in quite a few cancers." (PMID 30926679, 2019). "Furthermore, we observed reduced β-catenin and YAP staining in DKK3-null CAFs in vivo, and DKK3 expression significantly correlated with YAP/TAZ and β-catenin signatures in human cancer stroma." (PMID 30631061, 2019). "E2F3, miR-125a and DKK3 have been reported to be involved in various cancer types, but their detailed roles in GC have not been fully understood." (PMID 31423109, 2019). "We examined the DNA methylation levels of SFRP1, SFRP2, SFRP5, DKK2, DKK3, mir34b/c, RASSF1A, IGFBP7, CDKN2A, and MLH1 in normal colonic crypts isolated from regions that were adjacent to the cancer, as well as distal and proximal regions (left and right sides)." (PMID 28533824, 2017). "Despite its presumed role in regulating ß-catenin driven cancer cell proliferation, targeted inactivation of the mouse Dkk3 gene failed to provide a direct link between DKK3, the Wnt/ß-catenin signaling, and control of cell proliferation." (PMID 28738084, 2017). "We and other investigators have demonstrated that REIC/DKK-3 overexpression by adenoviral or plasmid vectors induces apoptosis in multiple cancer cell lines, but not in normal cells, via c-Jun-NH2-terminal kinase (JNK) and c-Jun activation." (PMID 26658102, 2016). "Our three biomarker panel consists of IGFBP2, DKK3 and PKM2, and each of these proteins are known to be biologically important in CRC disease and progression and are representative of the heterogeneous nature of this cancer." (PMID 25793510, 2015). "It has been shown that the expression of Wnt antagonists are often down‐regulated in several human cancers and DKK3 was no exception." (PMID 26395974, 2015). "As the REIC/Dkk-3 gene expression is absent or lacking in cancer cells, the REIC/Dkk-3 expression and protein folding system in cancer cells does not function well when the protein is overexpressed by Ad-REIC." (PMID 24527065, 2014). "Hypermethylation in the REIC/Dkk-3 promoter region has been previously reported in cancer cells with an absent or reduced expression." (PMID 24527065, 2014). "We compared the REIC/Dkk-3 expression levels between the CMV promoter-driven adenoviral vectors (Ad-CMV-REIC and Ad-SGE-REIC) and demonstrated significantly enhanced REIC/Dkk-3 gene expression by the SGE system in the human cancer cells." (PMID 24398705, 2014).
cancer (continued). "To investigate a mechanism for the reduced expression of the Dkk-3 gene, we analysed Dkk-3 promoter, which is known to be methylated in cancer cell lines lacking Dkk-3 expression." (PMID 15226763, 2004). "However, some studies have demonstrated that DKK3 expression does not always decrease in cancer, and its function is context-dependent." (PMID 36376957, 2022). "Taken together, translational studies that assess and modulate Dkk-3 expression and activity may lead to new avenues for the prognosis, prevention, and treatment of cancer and non-cancer diseases." (PMID 36497305, 2022). "Under physiologic and pathologic conditions, DKK-3 is able to regulate angiogenesis and several studies have reported an increase in the number of blood vessels expressing higher amounts of DKK-3 compared to its normal counterparts in different types of cancer." (PMID 34451907, 2021). "Thus, DKK3 is a novel HSF1 target gene that regulates ECM remodelling and associated cancer cell growth and invasion; unlike other HSF1 target genes such as TGFβ or SDF1, DKK3 does not have any apparent secreted function." (PMID 30631061, 2019). "Previous studies showed that overexpression of REIC/Dkk-3 using adenoviral or plasmid vectors induces apoptosis in various cancer cell lines, but not in normal cells, via c-Jun-NH2-terminal kinase (JNK) and c-Jun activation, and endoplasmic reticulum (ER) stress signalling." (PMID 28599655, 2017). "Although adenovirus vectors carrying appropriate tumor suppressor genes, such as REIC/Dkk-3, have great potential for cancer gene therapy, they do not exhibit target specificity and therefore may also infect normal cells in the vicinity of cancer cells." (PMID 24498395, 2014). "In addition, in the comparison between the Ad-CAG-REIC and Ad-SGE-REIC vectors by a western blot analysis in multiple human cancer cell lines, robust upregulation of REIC/Dkk-3 expression was observed in the Ad-SGE-REIC-transfected cells, particularly after the transfection at 10 MOI." (PMID 24398705, 2014). "Therefore, the lack of REIC/Dkk-3 expression has been found to positively correlate with the malignant grade and progression of cancer in several cancer types." (PMID 24527065, 2014). "In addition, our findings strongly suggest careful considerations whether or not DKK3 may be used as a therapeutic “agent” or “target” in the treatment of cancers." (PMID 26734010, 2015). "In addition, the abundant REIC/Dkk-3 protein expression and secretion after intratumoral Ad-REIC administration could provide anticancer immunological effects via a mechanism involving autologous cancer vaccination." (PMID 24398705, 2014). "Therefore, it can be speculated that lack of Dkk-3 expression favours the activation of the most powerful Wnt protein related to the development of cancer." (PMID 15226763, 2004). "Thereafter, REIC was found to be identical to human DKK3 and found not to be expressed in the majority of cancer cell lines." (PMID 36497305, 2022). "DKK3’s role in CSC has not been reported and its role in cancer has been controversial." (PMID 33828085, 2021).